IL15 (interleukin 15)
Diseases named in the same sentence as IL15 in open-access papers (continued):
Sharing a sentence is not in itself a finding about the gene and the disease.
tumor (continued). "As blocking IL15‐stat5a axis significantly dampened the Sell(hi) neutrophil‐mediated tumor cell killing capacity of p‐Stat5+ Tpex, we next assessed whether blocking this axis also reduced the antitumor efficacy of the C‐P regimen in MOC2 tumor‐bearing mice in vivo." (PMID 40936164, 2025). "Furthermore, IL-15/IL-21 demonstrated an increased capacity to enhance CAR-T tumor killing." (PMID 40291594, 2025). "Thus, while IL-15 is an appealing cytokine for amplifying immediate cytotoxic potential, IL-7 has better tolerability and exerts broader, more durable effects that favor long-term immune persistence and tumor control." (PMID 41550947, 2025). "Furthermore, the anti-tumor properties of IL-15, attributed to its capacity to support the survival, proliferation, and effector functions of NK cells and CD8+ CTLs, have been substantiated in both preclinical models and clinical trials involving patients with RMS." (PMID 41007114, 2025). "Importantly, MSC-sourced IL-15 not only enhances viability and expansion of NK cells, but also up-regulates expression of cytotoxic molecules (perforin, granzyme B, and Fas ligand (FasL)), thereby augmenting their ability to directly kill tumor cells." (PMID 40643499, 2025). "Additionally, these CAR-T cells achieved greater intratumoral IL-15 concentrations in the PDX tumor model compared to the combination of CAR-T cells and exogenous IL-15 administration, confirming the therapeutic advantage of endogenous IL-15 secretion in preclinical models." (PMID 41455698, 2025). "Additionally, cytokines, such as interleukin-12 (IL-12) and interleukin-15 (IL-15), are being investigated for their potential as cancer immunotherapies because of their ability to enhance anti-tumor immunity and promote the proliferation and activation of immune effector cells." (PMID 40650089, 2025). "Thus, the NK cells conditioned by means of IL-15 and IL-12 possess anti-tumor activities in vitro." (PMID 39835538, 2025). "The specific receptor of IL-15 (IL-15Rα) is secreted primarily by NK, T, and B cells.Binding of IL-15R to IL-15Rα produces the IL-15R/IL-15Rα complex, which binds to the IL-2Rβγ (IL-15Rβγ) expressed by effector cells (NK, T, and B cells), and further activates them to kill tumor cells." (PMID 40469178, 2025). "Notably, cytokine-expressing NK cells, including CD19IL15 CAR-NKs, IL-15 NKs, and IL-21 NKs exhibited a small peak in cytotoxic NK cell ratios, corresponding to the transition of a subset of cytotoxic NK cells into the vigilant phenotype upon tumor clearance." (PMID 40027823, 2025). "In addition, fourth-generation receptors, also known as TRUCKs (T cells Redirected for Universal Cytokine Killing), were designed to modify the TME and recruit other immune cells to generate a robust immune response by secreting cytokines (e.g. IL-12 and IL-15) into the tumor." (PMID 41346587, 2025). "To determine if a second dose of IL-15 complex could further enhance the efficacy of anti-PD-1 therapy, we next included a second intratumoral injection of IL-15 complex ten days following tumor inoculation (i.e., four days after the first dose of IL-15 complex)." (PMID 41373645, 2025). "Thus, there is a need to consider how NK cells respond to IL-15 and how tumor-localized production of IL-15 (or IL-2, IL-21, or IL-10) is affected by therapeutics and how this therapy can be customized to address the likely insufficient cytokine receptor agonism within the TME." (PMID 40410571, 2025). "Future studies are needed to determine whether the route and dosing of bifunctional anti-PD-L1/IL-15 superagonists, delivered subcutaneously, or of immunotherapies delivered directly into the tumor can modulate the immune system to convert treatment-refractory patients into responders." (PMID 41373645, 2025). "Therefore, interventions targeting IL15 would be expected to block tumor growth and spread." (PMID 40070829, 2025).
tumor (continued). "Additionally, IL15 has the potential to bind with IL15Rα on cancer cells, promoting their proliferation and migration independently of IL15Rβ/γc, thus counteracting its immunological anti‐tumor efficacy." (PMID 39625860, 2025). "Moreover, IF staining of the HA tag validated the presence of HA-tagged IL-15 in the tumor sites." (PMID 40532661, 2025). "Intratumoral treatment with two doses of IL-15 complexes alone generated partial responses in 42% of mice (five out of twelve), in which these mice showed significantly delayed tumor progression compared to vehicle control, while promoting tumor clearance in 58% of mice (seven out of twelve)." (PMID 41373645, 2025). "Furthermore, to clarify whether targeted CAF elimination was responsible for tumor inhibition by FAP/IL-15 CAR-T cells, we analyzed the expression of FAP and collagen type I in treated tumor tissues." (PMID 41455698, 2025). "Notably, α-HB subtype 2 exhibited significant enrichment in various immune and inflammatory pathways, including regulation of response to tumor cells, synaptic vesicle localization, and multiple interleukin-mediated signaling pathways (such as IL-6, IL-4, IL-2, and IL-15)." (PMID 41041634, 2025). "In addition to the reduced potency of immunocytokines and the local delivery and tumor conditional activation of IL-15, the identification and targeting of IL-15 signaling checkpoints is also gaining interest as an approach to increase the therapeutic index of targeting IL-15R." (PMID 40410571, 2025). "Additionally, using IL-15 superagonists to activate this pathway can mimic the anti-tumor effects of exercise, including tumor growth inhibition, prolonged survival, and enhanced chemotherapy efficacy, providing a new theoretical basis for PC treatment strategies." (PMID 39958351, 2025). "Finally, another group of constructs (anti-GD2RLI, 2B8T2M, IL15 trike) exploits the targeting mediated by a specific antibody for a tumor-associated antigen (TSA) to direct the activity of effector cells activated by the IL15/IL15Rα sushi domain complex to tumor cells." (PMID 39858511, 2025). "By combining cytokines (IL-12+IL-15+IL-18) to induce a memory-like phenotype, CAR-NK cells can acquire CD45RA-associated memory characteristics, with in vivo persistence extended beyond 60 days, and exhibit accelerated response kinetics upon secondary tumor challenge." (PMID 41488873, 2025). "The preferential stimulation and resulting uptake of IL-2/IL-15 therapeutic agents by the peripheral blood natural killer (NK) cells may limit the exposure needed to activate CD8+ T cells within the tumor environment, as intratumoral CD8+ T cells have been associated with efficacy." (PMID 39965362, 2025). "Additionally, using an LLC lung metastasis model, we showed that tumor cells transfected with IL-15 exhibited dramatically increased sensitivity to anti-PD-L1 therapy, although the overexpression of IL-15 in tumor cells potentiated their ability to metastasize to the lung." (PMID 38637902, 2024). "In mammals, IL-15 activates T cells, B cells, and NK cells and mediates the proliferation and survival of these cells, which has also been explored for therapeutic applications in different infections due to the important role of IL-15 in anti-tumor, pro-inflammatory, and anti-infection." (PMID 39628491, 2024). "Thus, our data showed that cancer cell-intrinsic IL-15 promotes tumor metastasis in vivo." (PMID 38637902, 2024). "In addition, the local production of soluble IL-15 in the tumor micro environment (TME) may be a critical component to increase antitumor immunity by activating the already present tumor reactive lymphocytes." (PMID 38690288, 2024). "Indeed, our study showed that the overexpression of IL-15 in tumor cells facilitated antitumor immune responses, as evidenced by an increase in the number and enhancement of effector functions of CD8+ T cells in tumors compared to those in wild-type LLC tumors." (PMID 38637902, 2024).
tumor (continued). "Notably, tumor necrosis, which is characterized by shrunken nuclear fragments and clusters of dead and degraded tumor cells, was observed, indicating that intracellular IL-15 can be released from dead Lv-mIL-15 LLC cells." (PMID 38637902, 2024). "Given the benefits of IL-15 as well as the overexpression of B7-H3 in NB patients, it might be relevant to pursue these immunotherapeutics in preclinical trials for this tumor." (PMID 39294470, 2024). "The aAPC platform was used to rapidly amplify tumour-infiltrating lymphocytes from primary tumour specimens, based on the Carl H June designed aAPC-K32, and further co-transfection with co-stimulatory molecule 4-1BBL and allowing it to secrete IL-2, IL-15, or IL-21 cytokines." (PMID 39215816, 2024). "Therefore, we hypothesized that induced pluripotent stem cell (iPSC)-derived NK cells, with an IL-15 knockin (KI) and TGFβR2 knockout (KO) could exhibit improved immune function and overcome the immunosuppressive tumor microenvironment (TME)." (PMID 39260365, 2024). "To determine whether IL-15 overexpression-mediated activation of the AKT-mTORC1 pathway is responsible for the upregulation of vimentin expression, we used LY294002 and rapamycin to inhibit AKT and mTORC1 activity, respectively, in cultured IL-15-overexpressing tumor cells." (PMID 38637902, 2024). "Interestingly, this NKCE was also able to increase NK-cell infiltration into subcutaneous tumours formed from breast cancer cell lines compared to functionally equivalent IL-15 and could enhance the proliferation of NK cells." (PMID 38223411, 2024). "Additionally, high levels of IL-15 expressed by tumor cells might improve the responsiveness of tumors to immunotherapies." (PMID 38637902, 2024). "We thus examined whether the IL-15-IL-15Ra complex can affect tumor cell migration." (PMID 38637902, 2024). "Therefore, local secretion of IL-15 might shape the immune-modulating environment of the tumor and elicit T and NK-cell mediated anti-tumor responses." (PMID 38690288, 2024). "Thus, use of IT MS~RLI or MS~IL-15 alongside with other agents could be advantageous for treating the primary tumor and preventing remote metastatic lesions." (PMID 39559362, 2024). "Thus, cancer cell-intrinsic IL-15 acts as a double-edged sword in tumor progression." (PMID 38637902, 2024). "To determine whether iCD8α+ NK cells retained their enhanced functionality over longer time periods, we injected sorted CD8α+ and CD8α– CD56dim NK cells into NSG mice, infused them with K562 tumor cells the following day, and supported this with i.p. injections of IL-15." (PMID 38805302, 2024). "However, chronic inflammatory stimulation of IL-15 increases tumor growth and metastasis." (PMID 37818360, 2023). "This article explored whether there is a correlation between IL-15, NK cells, and tumor apoptosis." (PMID 37585912, 2023). "There is also evidence that tumor cells could be a source of IL-15." (PMID 38567059, 2023). "Furthermore, the IL-15 cytokine has been studied for its ability to improve anti-tumor function." (PMID 37158883, 2023). "Interestingly, during CAR T cell development, addition of merely IL-15 enhanced similar beneficial effects, amongst others reduction of exhaustion, the preservation of a less differentiated memory cell phenotype and a superior anti-tumor response in-vivo." (PMID 36776340, 2023). "Therefore, this study aimed to explore whether IL-15 modification would increase the antitumor activity of CLDN18.2-targeting CAR-modified T (CAR-T) cells in immunocompetent murine tumor models." (PMID 37564658, 2023). "Thus, it is assumed that persistent exposure to tumor-induced IL-10 may exhaust NK cells as reported for IL-15 induced exhaustion." (PMID 36830840, 2023).
tumor (continued). "However cyto-IL-15 exerts its anti-tumor effects approximately 14 days after treatment and samples in that study were collected at survival endpoint (~28 days post-treatment), whereas the tumors in the present study were collected only at 6 days post-treatment." (PMID 37465665, 2023). "Notably, the interaction between T cell receptor (TCR) and biNV could promote the targeted delivery of IL-15 to tumor-specific T cells, which subsequently facilitates synergistic antitumor T cell responses." (PMID 37875481, 2023). "For example, the IL15_IL15RA interaction produces a two-sided effect, with IL-15 promoting the proliferation and maintaining the survival of certain T cells as well as consistently promoting anti-tumor responses and being crucial for controlling tumor growth and metastasis in vivo." (PMID 37818360, 2023). "N-803 (ALT-803), which is an IL15 cytokine antibody fusion protein, is a complex of the IL15 superagonist and the dimer IL15 receptor α Su/IgG1 Fc fusion protein, and it has been studied in combination with other agents in preclinical trials, which revealed an additive tumor suppression effect." (PMID 38067259, 2023). "The IL-15-mediated expansion of NK cells and their anti-tumor effector functions, mediated via antibody-dependent cellular cytotoxicity and the expression of other receptors involved in tumor cell killing, including NKG2D, NKp30 and DNAM-1, are attenuated by TGF-β1." (PMID 37569299, 2023). "Hence, it is speculated that the release of IL-15 after long-term regular exercise is involved in the targeted recognition of NK cell maturation and activation of tumor cell apoptosis signals." (PMID 37585912, 2023). "Interestingly, it has been reported that polyriboinosinic-polyribocytidilic acid (poly I:C)-treated macrophages increased NK cell-mediated cytotoxicity against tumor cells through increased surface expression of RAE-1 (an NKG2D ligand) as well as production of IL15." (PMID 37570749, 2023). "Moreover, we demonstrated that gene-based IL-15 delivery could sensitize the tumor microenvironment for immune checkpoint therapy with K2-Fc." (PMID 37923822, 2023). "Moreover, IL-15+biNV further delayed tumor recurrence in comparison with biNV." (PMID 37875481, 2023). "Similarly, it has been shown that tumor exosomes could impair IL-15-mediated up-regulation of NKG2D." (PMID 35031075, 2022). "Activation of IL-15 signaling further promoted mTOR-mediated metabolic fitness, including more efficient glycolysis and oxidative phosphorylation activity, which directly augmented the anti-tumor activity of CISH-knockout NK cells under low cytokines concentration." (PMID 36428748, 2022). "To test the potential requirement for the activation of the cGAS/STING pathway, which leads to IL-15 production in myeloid cells which have taken up the nanoparticles in vitro, in ONP-302-induced regulation of tumor growth, we examined B16.F10 tumor growth in STING-deficient C57BL/6 mice." (PMID 36059473, 2022). "Moreover, patients with CRC with genomic deletion of IL‐15 have reduced lymphocyte proliferation and a higher risk of tumor relapse than patients without IL‐15 deletion." (PMID 35791509, 2022). "Therefore, manipulation of the TME to induce IL-15 might prove to be a useful strategy for future anti-tumor therapies." (PMID 36372017, 2022). "Moreover, the aberrant IL-15 expression may be related to the tumour immune microenvironment in multiple types of cancer." (PMID 36467072, 2022). "Moreover, the suppressive effect of CD40 agonist/IL15 could still be observed in re-challenge experiments after a 100-day tumor-free period." (PMID 35453676, 2022). "Importantly these cells were dependent on IL-15 and displayed toxicity against tumor cells." (PMID 36032129, 2022). "Thus, PD-L siRNA IL-15 DCs might also be beneficial in the generation of a less immune suppressive tumor micro-environment." (PMID 35250967, 2022).
tumor (continued). "In addition, it is argued that long-term exposure to IL-15 may modulate the tumor microenvironment and promote tumor evasion." (PMID 35806311, 2022). "In this way, PD-L siRNA IL-15 DCs might reinvigorate exhausted tumor-reactive CD8+ T cells." (PMID 35250967, 2022). "IL-15 may be in synergy with ferroptosis/cuproptosis inducers for tumor treatment in the future." (PMID 36467072, 2022). "Given this successful improvement of the stimulatory capacity of IL4 DCs, we subsequently showed that combining in situ downregulation of PD-L1 and PD-L2 with introduction of interleukin-15 transpresentation tools could further potentiate tumor-reactive T-cell expansion." (PMID 35250967, 2022). "Proinflammatory cytokines such as IL-15 are, conversely, produced by healthy cells, and contribute to remove leukemic blast cells and also to generate memory stem T-cells from naïve T-cells, contributing to the immunologic counterresponse directed to tumor cells." (PMID 36530990, 2022). "Additionally, CD4-IL15/IL15sushi CAR cells outperformed CD4 CAR cells in vivo, reducing tumor burden and providing survival benefit, suggesting that the secreted IL15/IL15sushi complex may be beneficial in the treatment of T-cell malignancies." (PMID 36172388, 2022). "Finally, the authors wanted to uncover the primary source of IL-15 within the tumor micromilieu." (PMID 36115839, 2022). "Although the mechanisms of interaction between IL-15 and chemotherapeutics need to be further clarified, it could be the result of the combined cytotoxic effect of drugs on tumor cells together with stimulation of an antitumor immune response by the IL-15/IL-15α complex." (PMID 33916844, 2021). "The addition of IL-15 to this combination may thus further augment NK cell anti-tumour responses." (PMID 34888493, 2021). "However, IL-15 must form the IL-15/IL-15Rα complex in order to exert its tumor immune function." (PMID 34386015, 2021). "Furthermore, we observed a marked decrease of PD-1–expressing CD3+ T cells in the peripheral blood, and CD3+ T cells showed a statistically significant decrease in the proportion of PD-1+ cells in response to IL-15 stimulation and PD-1 blockade in both the spleen and tumor of TIL-PDX-LUAD mice." (PMID 34081628, 2021). "Interestingly, co-administrating the engineered T cells expressing NY-ESO1 and membrane-bound IL-15 could robust the anti-tumor cytotoxicity and persistence of memory CAR-T cells." (PMID 33781320, 2021). "Studies have shown that DCs could cause this discrepancy of IL-15 levels acting both as a positive or a negative marker in regard to tumor evolution and survival outcome and its effect on the Immune system." (PMID 32929618, 2021). "NK cells target tumor cells sensitized by monoclonal antibodies specific for tumor associated antigens GPC-3 or AFFP on tumor cells by mediating ADCC and this would also be a promising therapeutic strategy after activation of NK cells with cytokines such as IL-15." (PMID 34071188, 2021). "Exploiting IL-15′s influential properties to improve lymphocyte effector function in the setting of malignancy is likely to become more structured in the future and might lead to a broader use in the treatment of tumor malignancies." (PMID 32929618, 2021). "In addition, in this case, expression may be influenced by cytokine milieu in the tumor microenvironment, which selects, through the epigenetic role of some cytokines (TGF-β, IL-15 and IL-18), the NKp30 inhibitory variant and affects NK cell cytotoxicity." (PMID 33802077, 2021). "Therefore, interleukin-15 administration combined with cancer cell-targeted near infrared photoimmunotherapy could further inhibit tumor growth by increasing antitumor host immunity." (PMID 32927646, 2020). "However, in our study IL-15 or IL-15cx treatment has been shown to decrease MDSCs in tumor mice." (PMID 33628206, 2020). "Thus IL-15 deficiency can be immunosuppressive in the TME of CRC and assist tumor progression." (PMID 33419310, 2020).